IL6 (interleukin 6)
Diseases named in the same sentence as IL6 in open-access papers (continued):
Sharing a sentence is not in itself a finding about the gene and the disease.
depression (continued). "Chronic activation of pro-inflammatory cytokines, including tumor necrosis factor-alpha (TNF-α), interleukin-1 beta (IL-1β), and interleukin-6 (IL-6), is observed in both PH and depression." (PMID 39941652, 2025). "IL-6 leads to neural progression by promoting astrocyte apoptosis and contributes to the occurrence of depression." (PMID 40530060, 2025). "Evidence from both animal and clinical studies suggests that elevated levels of the pro-inflammatory cytokine IL-6 in the peripheral blood or central nervous system play an important role in depression." (PMID 40708589, 2025). "Depression trajectories and mean depressive scores across all IL-6 tertiles were generally worse in females compared to males." (PMID 39865800, 2025). "The fact that IL-6 represents a probable biological pathway through which inflammation can contribute to symptoms of depression becomes important in clinical practice in patients with pSS." (PMID 40822847, 2025). "While studies have highlighted the role of inflammatory markers such as CRP and IL-6 in depression, PHR offers distinct advantages by integrating two measurable and routinely assessed parameters: platelet count and HDL cholesterol." (PMID 40606819, 2025). "Concurrently, these metabolic shifts enhance systemic inflammation by amplifying IL-6 and TNF-α release, priming microglia, and compromising the BBB integrity, mechanisms long implicated in depression and other affective disorders." (PMID 41244880, 2025). "Small trials of cytokine inhibitors (e.g., anti-TNF agents or IL-6 blockers) in treatment-resistant depression have shown modest benefits." (PMID 41149069, 2025). "Individuals with PTSD and depression frequently show elevated levels of pro-inflammatory markers, such as interleukin-6 (IL-6) and C-reactive protein (CRP)." (PMID 41347040, 2025). "This study investigated the possible connection between IL-6, the acute phase of multiple sclerosis, and depression." (PMID 40313235, 2025). "This metabolic dysregulation further contributes to chronic inflammation, promoting the release of pro-inflammatory cytokines such as IL-6 and TNF-α, which have been implicated in both depression onset and severity." (PMID 40177085, 2025). "Testing using the FST revealed that depression-like behavior was affected by serotonin levels in the hippocampus and serotonin, cortisol, IL-6, and NF-κB levels in the prefrontal cortex area." (PMID 39911318, 2025). "Increase levels of IL-6 are observed during the acute phase of the disease, especially when depression is detected." (PMID 40313235, 2025). "IL-6 has also been shown to play an important role in the diagnosis and treatment of depression, as it is believed to trigger the body's immune response under stress." (PMID 41312464, 2025). "Chronic stress and unresolved depression induce pro-inflammatory signaling, leading to increased circulation of IL-6, TNF-α and IFN-γ, further driving malignancy, angiogenesis, and immune evasion." (PMID 40943040, 2025). "IL-6, in particular, appears to be a key mediator in the link between depression and Long COVID, contributing to immune dysregulation by altering the balance between TH17 and Treg lymphocytes and affecting brain regions associated with mood regulation." (PMID 41268373, 2025). "The present study utilized IL-6 and NF-κB proinflammatory cytokines, alongside serotonin and cortisol as neurotransmitter markers, given their involvement in depression pathology." (PMID 39911318, 2025). "IL-6 is a significant cytokine that is elevated in depression and plays a role in influencing the HPA axis, neurotransmission of serotonin, and mood regulation." (PMID 40821217, 2025). "In patients with AS and depression, elevated levels of the inflammatory factors IL-6 and IL-10 are observed, while ferroptosis exerts a significant pro-inflammatory effect." (PMID 40066336, 2025).
depression (continued). "The pro-inflammatory cytokines TNF-α, IL-17, and IL-6 play a crucial role in both psoriasis and depression by driving chronic inflammation in the skin and neuroinflammation in the central nervous system." (PMID 40141110, 2025). "Results show that patients with depression had significantly higher increases at 2 years compared to baseline for all investigated parameters (CRP—p = 0.032/Fibrinogen—p = 0.030/Interleukin-6—p < 0.001/TNF-α -p = 0.007/Cortisol—p < 0.001)." (PMID 40363978, 2025). "The inflammatory markers demonstrated positive relationships with neuropsychological test results because CRP and IL-6 concentrations increased with higher depression and anxiety scores." (PMID 41451009, 2025). "In summary, our results describe for the first time a relationship between SI and the IL-6-induced stimulatory capacity of the STAT3-expressing PBMCs in the context of depression." (PMID 40115872, 2025). "Genome-wide analyses demonstrate significant enrichment of immune-related pathways (e.g., IL-6 signaling and natural killer cell pathways) in patients with Depression." (PMID 40508038, 2025). "Logistic regression identified IL-6 as an independent predictor of depression (OR = 3.23, 95%CI: 1.07 - 9.80, P = 0.038), while ESSPRI fatigue was a significant predictor of anxiety (OR = 2.01, 95%CI: 1.13 – 3.58, P = 0.018)." (PMID 40822847, 2025). "Due to previous observational longitudinal and MR studies showing stronger effects of serum IL-6 compared to CRP with depression, the focus of this study is on IL-6." (PMID 39865800, 2025). "Elevated C-reactive protein (CRP) and Interleukin-6 (IL-6) are consistently observed with sleep disturbance and with extreme sleep durations, and meta-analytic data in depression show increases in IL-6/ Tumor Necrosis Factor-Alpha (TNF-α) and CRP." (PMID 41662130, 2025). "C. difficile has also been shown to increase depression and anxiety-like behaviours in mice with increased levels of IL-6 both in the colon and hippocampus." (PMID 41462928, 2025). "Participants who received the combined treatment showed significant improvements: ~25% cortisol reduction, ~3 kg weight loss, decreased IL-6 and TNF-α levels, and better scores on the Beck Depression Inventory-II and Perceived Stress Scale." (PMID 40649341, 2025). "A previous meta‐analysis has shown that increased microglial activity induces increased levels of TNF, interleukin‐8 (IL‐8), and IL‐6 in cerebrospinal fluid (CSF) and brain tissue of patients with depression." (PMID 40202374, 2025). "Meta-analysis showed that IL-6 was significantly lower in the test group compared with the control group (SMD: −1.89, 95% CI: −2.51, −1.26), indicating that depression animals treated with acupuncture had significantly lower levels of IL-6 (P<0.05)." (PMID 41244868, 2025). "Elevated basal pro-inflammatory markers (e.g., IL-1β, IL-6) are typical in individuals vulnerable to depression, while resilience aligns with lower levels and immune-quiescent microglia." (PMID 41227125, 2025). "Since serum IL-6 level was highest in the HSB group, which is characterised by high levels of anxiety and depression, we also analysed the correlation between serum IL-6 level and anxiety and depression scores." (PMID 41050477, 2025). "Increasing evidence links neuroinflammation with the pathogenesis of depression, as patients with major depressive disorder often exhibit elevated circulating levels of inflammatory markers, such as interleukin-6 (IL-6)." (PMID 40809378, 2025). "A longitudinal study of 47 patients with PD confirmed that elevated IL-6 levels at baseline showed worse depression scores, and higher levels of C3 and C4 at baseline decreased quality of life after 2 years." (PMID 40672460, 2025). "The results show that CSDS induces significant anxiety‐ and depression‐like behaviors, along with notable astrocyte atrophy and apoptosis, microglial activation, and elevated levels of microglial interleukin‐6 (IL‐6)." (PMID 39888279, 2025).
depression (continued). "Concurrently, inflammatory cytokines involved in the pathophysiology of depression, such as IL-6 and TNF-α, directly affect bone metabolism by stimulating osteoclast activity and inhibiting osteoblast function, thereby disrupting bone homeostasis." (PMID 40718425, 2025). "For instance, IL-6 is consistently elevated in both depression and cardiovascular disease, yet its predictive value for dual comorbidities is not well established." (PMID 40218134, 2025). "The polarization of microglia and the level of pro-inflammatory cytokines TNF-α, IL-1β, and IL-6 have been widely used to assess neuroinflammation in Alzheimer’s disease, major depression, ASD, and ADHD." (PMID 40429903, 2025). "IL-6, a pro-inflammatory cytokine commonly elevated in depression, showed a significant reduction 24 h post-ketamine administration after a transient increase 4 h after ketamine." (PMID 40806626, 2025). "For example, patients with psoriasis and comorbid depression have shown elevated serum concentrations of IL-6, IL-18, and IL-17A." (PMID 40077004, 2025). "Both preclinical and clinical studies have found higher levels of IL-1β, TNF-α, and IL-6 in peripheral blood and brain tissue of patients with depression." (PMID 41561993, 2025). "Certain biomarkers elevated in inflammatory and chronic disease states are also found to be increased in depression.Interleukin-6 (IL-6), tumor necrosis factor-α (TNF-α), and cortisol have been linked to depression and are associated with symptom severity." (PMID 40098072, 2025). "For instance, patients experiencing pain, fatigue, depression, and sleep disorders have been found to exhibit poorer performance status and significantly higher levels of interleukin-6 (IL-6)." (PMID 40755751, 2025). "In contrast to IL-6, TNF-α and IL-1β levels were both associated with an increased odds of actually meeting criteria for clinical depression." (PMID 39902492, 2025). "Ischemic injury post-AMI triggers an inflammatory cascade, with elevated pro-inflammatory cytokines (IL-1β, IL-6, TNF-α, sICAM-1), which have been linked to depression and anxiety." (PMID 40142595, 2025). "The role of IL-6 in targeting BDNF responses for neuroregeneration and the treatment of depressive disorders is critical, particularly as exercise is associated with elevated BDNF levels." (PMID 40843259, 2025). "Its extracellular form acts as a pro-inflammatory cytokine that promotes the secretion of IL-6, TNF-α, and IL-1β, molecules that are closely linked to depressive disorder." (PMID 41375608, 2025). "Analyses have shown that a functional single-nucleotide polymorphism (SNP) in the promoter region of the IL-6 gene leads to elevated values of IL-6 and CRP, which correlate with the severity of depressive syndrome." (PMID 40699818, 2025). "Elevated IL-6 concentrations have been observed in individuals with depression, and some studies have additionally reported increased levels of IL-6 and its receptor antagonist in patients with treatment-resistant MDD." (PMID 41226404, 2025). "Patients with anxiety and depressive disorders have increased levels of pro-inflammatory cytokines (e.g., TNFα, IL-1α, IL-1β, IL-4, IL-5, IL-6, IL-12, and interferon [IFN]-γ) and C-reactive." (PMID 39803412, 2025). "The levels of interleukin-1 beta (IL-1β), interleukin-6 (IL-6), and tumor necrosis factor (TNF) are associated with anxiety behavior and also with more severe depressive disorders." (PMID 40563433, 2025). "An increased concentration of IL-6 in patients suffering from PsA and depressive disorder compared to the PsA-group was also confirmed in a different research." (PMID 40141110, 2025). "It has been shown to protect against CUMS-induced depression by enhancing the gut microbiome’s reconstruction and reducing inflammation in the colon by downregulating the expression levels of IL-6, IL-1β, and TNF-α." (PMID 39459643, 2024).
depression (continued). "Only one other study has examined gene expression changes after probiotic administration in patients with depression, reporting higher IL-6 expression post-intervention." (PMID 39048549, 2024). "In patients with depression, activated monocytes release elevated levels of IL-6, exacerbating this process." (PMID 39723161, 2024). "5-HT, BDNF, IL-6, and NO are all closely related to depression and are vital indicators for judging the severity of depression." (PMID 39062817, 2024). "Preliminary evidence, using MR, implicate IL-6 and its soluble IL-6 receptor (sIL-6R) in depression." (PMID 38699368, 2024). "Individuals with COPD with symptoms of depression and anxiety have elevated systemic levels of inflammatory cytokines such as interleukin-6 (IL-6) and IL-1β." (PMID 39061923, 2024). "People who suffer from depression have increased concentrations of inflammatory state markers, such as interleukin 6 (IL-6), tumor necrosis factor-alpha (TNF-α), and other interleukins, while interferon-gamma (IFN-γ) levels are decreased." (PMID 38732635, 2024). "For example, elevated concentration of C-reactive protein (CRP; >3 mg/L) has been detected in 21%–34% of patients with depression, along with increased concentrations of IL-6 and other inflammatory cytokines in blood and in cerebrospinal fluid (51, –, 54)." (PMID 38421192, 2024). "Yet, it was shown that this effect was reversed in mice deficient in IL-6, whose hippocampal SERT levels were higher and whose depression symptoms were lower." (PMID 39273641, 2024). "With IL6, we have found a classical relationship, that higher levels of IL6 were observed in suicide attempt patients (6.56 ± 6.90), depression group (4.43 ± 3.39) vs 3.46 ± 1.28 in controls, however, the significance level was not achieved (p = 0.34)." (PMID 38737407, 2024). "Upon activation, microglial cells release inflammatory cytokines, such as IL‐6, TNF‐α, and IL‐1β, which are associated with the neuronal degeneration often observed in depression." (PMID 39554370, 2024). "A meta-analysis comprising individuals both with and without cardiovascular disease demonstrated a correlation between elevated levels of C-reactive protein (CRP), IL-1, and IL-6, and depression." (PMID 38809848, 2024). "Inflammatory markers such as C-reactive protein (CRP) and interleukin-6 (IL-6) are often elevated in individuals with depression, diabetes, and prediabetes." (PMID 39457589, 2024). "Repeated measures of proinflammatory markers (e.g., hs-CRP and IL-6) over time would have provided more insights into the temporal relationship between inflammation and depression." (PMID 37848651, 2024). "The elevated levels of certain cytokines are associated with inflammation in the brain, including interleukin-1 beta (IL-1β), interleukin-6 (IL-6), and tumor necrosis factor-alpha (TNF-α), which has been linked to the pathophysiology of depression." (PMID 39513898, 2024). "Polymorphisms in genes such as IL-1β, IL-6, IL-10, TNF, MCP1/CCL2, CRP, and phospholipase A2 are among the most consistently observed findings in major depressive disorder." (PMID 39723161, 2024). "Other meta-analyses have suggested associations between depression and elevated levels of inflammatory markers, such as C-reactive protein (CRP), IL-6 and, to a lesser extent, IL-1." (PMID 39358787, 2024). "Depression can result in elevated levels of C-reactive protein, interleukin (IL)-1β, IL-6, and tissue necrotic factor-alpha, as well as an increase in the concentration of inflammatory molecules, such as NLRP3 inflammasomes." (PMID 39006364, 2024). "Regarding clinical studies, elevated inflammatory markers in blood samples such as C-reactive protein and IL-6 are often found in patients with depression and those with a history of suicide attempts." (PMID 39290301, 2024).
depression (continued). "According to a meta-analysis summarizing decades of research, using a random-effects model analysis, the correlations of IL-1 and IL-6 with depression were found to be higher than that of CPR." (PMID 39329797, 2024). "In contrast, S-ketamine mitigates IL-1b–induced TNF-a, as well as IL-6–induced IL-1b and IL-8, highlighting the importance of considering ketamine formulation in depression treatment." (PMID 39297528, 2024). "For example, IL-6 levels in people with type-2 diabetes or depression often range between 2 and 10 pg/ml." (PMID 38974339, 2024). "A recent study showed that Interleukin-6 (IL-6) was downregulated in the CA1 hippocampus in two animal models of depression, chronic unpredictable mild stress (CUMS) and lipopolysaccharide (LPS), and was upregulated by antidepressants." (PMID 38675471, 2024). "During manic episodes, IL-6, IL-5, interferon (INF)-γ and IL-8 were the upregulated pro-inflammatory cytokines, while only IL-6 was found to be raised during depression." (PMID 38672750, 2024). "Large-scale epidemiologic studies and meta-analyses have demonstrated a strong association between IL-6 or CRP and mortality outcomes from a variety of causes (including diseases such as cancer, cardiovascular disease and depression)." (PMID 38952546, 2024). "Chronic low-grade inflammation, characterized by the secretion of pro-inflammatory cytokines such as TNF-α and IL-6, is a central link between obesity and depression, establishing a vicious cycle where each condition can exacerbate the other." (PMID 39335507, 2024). "It has been shown that patients with major depressive disorders had increased inflammatory markers such as interleukin (IL)-1β, IL-6, tumor necrosis factor (TNF)-α and C-reactive protein (CRP)." (PMID 39394060, 2024). "Inflammatory markers, such as C-reactive protein, tumor necrosis factor-α, and interleukin-6, were elevated in both depression and migraine." (PMID 38881795, 2024). "Higher IL-6 levels in plasma of stroke patients prominently correlate with symptom severity of depression three months post-stroke, suggesting that IL-6 can be used as a potential PSD biomarker." (PMID 38421829, 2024). "In the RCT involving patients with multiple sclerosis, multi-strain probiotic supplementation over 6 months resulted in a significant increase in BDNF levels, a significant reduction in IL-6 levels, as well as significant improvements in depression scores." (PMID 38505265, 2024). "IL-6 levels independently correlate with a higher prevalence and severity of depression in this group of patients." (PMID 38999222, 2024). "This aligns with literature describing how HIV infection increases the release of tumor necrosis factor-α, IFN-γ, interleukin (IL)-1, and IL-6, resulting in reduced 5-hydroxytryptamine transmission and ultimately leading to depression in PWH." (PMID 39902245, 2024). "For example, in a study with 667 outpatients with CHD, greater depressive symptoms were associated with higher subsequent levels of IL-6 and CRP, and persistent depression had a greater effect on inflammation than a single episode of depression." (PMID 38820248, 2024). "Two meta-analyses have demonstrated that CSF concentrations of IL-6 are elevated in patients with major depressive disorder compared to controls." (PMID 38336728, 2024). "People with depression exhibit increased concentrations of biomarkers of inflammation, including cytokines such as interleukin-6 (IL-6) and tumour necrosis factor-alpha (TNF-α)." (PMID 38386679, 2024). "Elevated levels of cytokines like interleukin-6 (IL-6) and tumor necrosis factor-alpha (TNF-alpha) have also been linked to psychological conditions, including mood disorders such as depression and anxiety." (PMID 39618672, 2024). "Specifically, cytokines such as IL-1β, IL-6, and TNF-α, associated with depression, can induce thermoregulatory abnormalities leading to fever and HFs14." (PMID 39019875, 2024).